IL1B (interleukin 1 beta)
Diseases named in the same sentence as IL1B in open-access papers (continued):
Sharing a sentence is not in itself a finding about the gene and the disease.
Anxiety (continued). "At the end of the 12-week experiment, anxiety-like behavior was evaluated by the light/dark box test; compulsive-like behavior by Marble burying, transcriptional regulation of genes Lrrk2, Tlr4, Nfat, Drd1, Drd2, Il6, Il1β, Il10, and iNOS by RT-qPCR; and inflammatory markers by flow cytometry." (PMID 37063320, 2023). "Potential sources include leukocytes that may have infiltrated into the brain, microglia, astrocytes and neurons, with IL-1β produced from such cells interacting with IL-1R1 on neurons involved in the anxiety circuits and behaviors observed in the current study." (PMID 35379260, 2022). "Moreover, bergamot essential oil could relieve anxiety-like behaviors of aluminum trichloride-exposed rats via downregulating the levels of IL-1β, IL-6 and TNF-α in the hippocampus and the frontal cortex." (PMID 36358502, 2022). "The interdependence between IL-1R and anxiety may involve the observed phenomenon in which IL-1β promotes expression of IL-1 receptor type 1 and the accessory coreceptor AcP, rather than the synapse promoting AcPb subunit in hippocampal neuronal cultures, leading to impaired long-term potentiation." (PMID 33446652, 2021). "Moreover, inhibition of the NLRP3 inflammasome activation could reduce hippocampal IL-1β expression level and obviously improved the anxiety- and depressive-like behaviors in mice." (PMID 29495433, 2018). "After adjusting for the confounding variables, sex, and location of the data collection, anxiety-related behaviors were positively predicted by higher BCS, creatinine, and IL-10, and negatively predicted by IL-1β." (PMID 41268300, 2025). "The results show a significant correlation between anxiety behavioral indicators and CORT levels, inflammatory factors (IL-6, IL-1β, CD86, TNF-α, TGF-β, IL-10), 5-HT, and GABA." (PMID 40078708, 2025). "These cells release cytokines and chemokines, such as TNF-α, IL-1β, IFN-γ, IL-6, iNOS, etc., which ultimately lead to neuronal death and trigger anxiety." (PMID 39905541, 2025). "PS-MPs induced anxiety through activation of the PERK-NF-κB signaling pathway, mediated by HRAS, in microglia, with increased pro-inflammatory cytokines TNFα and IL-1β." (PMID 41303677, 2025). "Ethanol exposure increased anxiety and immobility in behavioral tests, consistent with depressive-like behaviors, and elevated TNF-α, IL-1β, and IL-6 levels." (PMID 40860877, 2025). "At this time, nuclear factor kappa-B, IL-1β, and tumor necrosis factor (TNF)-α in the brain will be significantly increased, promoting the anxiety state of mice, and administering L. reuteri can significantly improve this condition." (PMID 39076985, 2024). "Our findings suggest that solanesol inhibits neuro-inflammation by decreasing the TIA1 level to reduce IL-1β and TNF-α expression, meanwhile inhibiting microglial and astrocytic activation in the ACC and ultimately ameliorating anxiety-like behaviors in mice." (PMID 39337650, 2024). "The peripheral rise in corticosterone in the first 3 h of LPS exposure promote the increase in IL-1β, IL-6, and TNF-α, exerting an anxiety effect on the limbic system, including the hippocampus." (PMID 39057053, 2024). "Further, central GPR120 agonist pre-treatment was effective in attenuating sickness- and anxiety-like behaviors triggered by systemic LPS and central TNF-α and IL-1β administration." (PMID 38111048, 2023). "ROS induces the production of TNF-α and IL-1β by activating the NFkBp65-COX2-mPGES-1 signaling pathway, thus accelerating anxiety." (PMID 37273529, 2023). "The excessive IL-1β expression within areas of the SDMN were related with the asocial and anxiety-like behavior in MK-801-treated fish." (PMID 37284463, 2023). "The evidence from human studies shows a close relationship between prenatal exposure to pro-inflammatory cytokines, such as TNF-α, IL-1β, IL-6, IL-17a, and ASD, schizophrenia, anxiety, depression, and ADHD." (PMID 35937892, 2022).
Anxiety (continued). "As pro-inflammatory cytokines can influence anxiety- and depressive-like behaviors, we analyzed the expression of TNF, IL-6, and IL-1β in the hippocampus." (PMID 36333302, 2022). "In rodent models of stress-induced anxiety, activation of the NLR family pyrin domain-containing 3 (NLRP3) inflammasome and upregulation of IL-1β is noted in hippocampal and cortical brain regions and are critical for the onset of anxiety." (PMID 33446652, 2021). "In our present study, both peripheral and central IL-1β, IL-6, and TNF-α levels were significantly increased after CFA injection, and the injected mice showed obvious anxiety-like behaviors." (PMID 32019580, 2020). "Here, we found a similar trend between alcohol-induced anxiety with systemic and hippocampal BDNF and IL-1β levels." (PMID 32606350, 2020). "Significantly increased gene expression of Il-1β and Il-6 in SAMP8 control in comparison with SAMR1 mice was determined, confirming the inflammatory phenotype related to anxiety- and depressive-like behaviours presented by SAMP8." (PMID 32456135, 2020). "LPS-induced acute-sickness behavior, including anxiety- and depressive-like behavior was prevented by attenuating among TNF-α, IL-1β, and IL-6 levels of brain and plasma of mice." (PMID 31213027, 2019). "The effects of bicuculline on microglia and astrocyte activation, IL-1β content, on membrane expression of AMPA and NMDA glutamate receptors subunits in the hippocampus and on spatial learning and memory as well as anxiety were assessed." (PMID 30858801, 2019). "Nonetheless, a positive correlation was found between concentrations of IL-1β and scores for MDD and anxiety." (PMID 30662368, 2018). "Significant increases in brain levels of both IL-1β and TNFα were observed only in female offspring from HFD/HFD dams that were also the only group to display increased anxiety and decreased sociability." (PMID 25212412, 2014). "In addition, SCFAs can modulate microglia activation, influencing the release of pro-inflammatory factors, such as IL-1β, IL-6, and TNF-α, which can further impact neuroinflammation and anxiety-like behaviors." (PMID 41459223, 2025). "In the MIA mouse model of ASD, P. goldsteinii MTS01 ameliorated antisocial and anxiety-like behaviors by reducing colonic TNF-α, IL-6, and IL-1β in the intestines while increasing the activity of antioxidant pathways and decreasing glutamate receptor signaling in the hippocampus." (PMID 40804450, 2025). "Cilostazol reportedly prevented the development of anxiety symptoms and post-traumatic stress disorder (PTSD)-induced increases in hippocampal IDO and IL-1β, improving neuroinflammation, and has been proposed as a promising candidate for further PTSD pharmacotherapeutic research." (PMID 40969943, 2025). "Our findings are supported by a previous study demonstrating that AGOM treatment decreased the release of cytokines (TNF-α, IL-6 and IL-1β) and restored BDNF levels and the activity of the antioxidant enzymes CAT and GPx in the brain in an HFD-induced anxiety-like behavior model." (PMID 40076566, 2025). "The elevation of these cytokines (especially IL-1β, IL-6, IL-10, IFN-γ, and TNF-α) may have a role in stress and anxiety in infected patients." (PMID 39935742, 2024). "Here, we aimed to determine whether solanesol can reduce IL-1β and TNF-α levels by regulating TIA1 in the ACC, thereby improving anxiety-like behaviors in mice." (PMID 39337650, 2024). "Western blot analysis revealed that CFA-induced upregulation of the levels of pro-inflammatory cytokines interleukin (IL)-1β and tumor necrosis factor α (TNF-α), which played crucial roles in regulating anxiety, returned to normal in the anterior cingulate cortex (ACC) after solanesol treatment." (PMID 39337650, 2024).
Anxiety (continued). "The expression of IL-1β within the proliferation zones of adult zebrafish brain, following MK-801 treatment, was questioned since previous studies demonstrated that excessive IL-1β expression within areas of the SDMN, related with the asocial and anxiety-like phenotype of MK-801-treated fish." (PMID 37908201, 2023). "Next, we examined whether injections of IL-1β and TNF-α in the gums can modulate anxiety-like behavior and cognitive functions of mice." (PMID 36915108, 2023). "TNF-α induced by the hippocampal microglia is significantly elevated in mice exposed to acute stress, and cytokines (IL-1β, TNF-α) released by the microglia can inhibit neurogenesis in the dentate gyrus, thereby promoting neuronal apoptosis and increasing anxiety-related behavior." (PMID 36624089, 2023). "However, like the standard drug EZ group, FGL and FGH demonstrated improved anxiety-like behavior and reduced levels of TNF-α and IL-1β in the hippocampus of SD rats 7 days after the intervention." (PMID 37377643, 2023). "However reduced SD-induced anxiety-like behavior and decreased levels of pro-inflammatory cytokines including TNF-α and IL-1β were observed in the hippocampus of rats after 7 days of FG intervention." (PMID 37377643, 2023). "IL1β, TNFα and IL6 were evaluated in the medial prefrontal cortex, nucleus acumens and amygdala, structures known to play pivotal roles in motivational, social or anxiety behavioral processes." (PMID 36675275, 2023). "In animal models, for example, IL-1B induction of p38 mitogen-activated protein kinase (MAPK) increased the expression and function of serotonin reuptake pumps, resulting in decreased synaptic availability of serotonin and anxiety-like behavior." (PMID 35194013, 2022). "In addition, a red pomegranate fruit extract-based formula ameliorated anxiety-like behaviors through reducing the levels of serum inflammatory cytokines NF-κB, TNF-α, IL-6, IL-1β and IFN-γ." (PMID 36358502, 2022). "The relevant biomarkers assessed in the anxiety study population were CRP and IL-1β." (PMID 35053845, 2022). "We also used lipopolysaccharide (LPS), an agonist of TLR4, in an in vitro model of macrophage IL-1β and TNF release and in an in vivo paradigm of “sickness behavior,” measuring inflammation-induced signs of anxiety, hypolocomotion, and suppressed exploration in mice." (PMID 36091684, 2022). "High TNF-α (P=0.002, adjusted P=0.008), but not high IL-1β (P=0.864, adjusted P=1.000), IL-6 (P=0.160, adjusted P=0.640), and IL-17 (P=0.266, adjusted P=1.000), was correlated with anxiety occurrence." (PMID 35239774, 2022). "Production of IL-1β and NLRP3 were critical for both anxiety phenotypes and microglia activation." (PMID 33446652, 2021). "Intriguingly, the combination of stressors led to yet another phenotype with increased anxiety-like features, reduced serum IL-1β levels and hippocampal plasticity but without significant alterations in corticosterone reactivity and M/Ms activation." (PMID 34279714, 2021). "Together, our microglia analysis suggests inflammasome production of IL-1β promotes microglia phenotype responses in models of sleep deprivation and serves as a molecular substrate that can be targeted with FDP metabolites to promote resilience to anxiety." (PMID 33446652, 2021). "The observation that Nlrp3-/- mice do not exhibit anxiety phenotypes following sleep deprivation support that FDP metabolites reduced IL-1β in sleep deprivation models by inhibiting the NLRP3 inflammasome." (PMID 33446652, 2021). "As individual metabolites derived from FDP inhibited IL-1β production and NLRP3-deficit mice show suppressed anxiety in response to chronic sleep deprivation, this supports the conclusion that anxiolytic effects of FDP were in part due to suppressed NLRP3 activity." (PMID 33446652, 2021).
Anxiety (continued). "The relative mRNA level of the inflammatory cytokine, Il-1β, was also examined in the hippocampus and cerebral cortex in order to elucidate the intricate anti-inflammatory mechanism by which 0.5% GORZ regulates alcohol-induced anxiety." (PMID 32606350, 2020). "Two important biomarkers, BDNF and IL-1β in serum were assayed to establish a link of the regulatory mechanism of 0.5% GORZ treatment between the central nervous system (CNS) and the circulatory system under alcohol-induced anxiety." (PMID 32606350, 2020). "Since in previous study we showed the ability of Oxo treatment to abolish the anxiety-like behavior induced by CRS7, the findings of the present work clearly showed that chronic Oxo treatment may counteract the CRS effects on IL-1β and IL-6 levels." (PMID 31578381, 2019). "Animal studies have found that COX-2 inhibition attenuates neuroinflammation (hippocampal inflammatory markers cytokines IL-1β, TNF-α, and brain PGE2 levels) and circulating corticosterone, and may also alleviate symptoms of anxiety and cognitive decline." (PMID 31671812, 2019). "When TNFα was also knocked-down at the same time as S1PR3, the increase in anxiety-like behavior was reversed but IL1β knock-down with knock-down of S1PR3 did not produce behavioral changes different from S1PR3 knock-down alone." (PMID 31316053, 2019). "In children/adolescents with MDD or dysthymia and anxiety, IL-1β concentration was not significantly different from that of controls, and medication did not affect IL-1β levels." (PMID 30662368, 2018). "Because we found lower IL-1β mRNA levels in obese patients with anxiety/mood disorders (A/MD subgroup) than in patients without mental disorders (non-MD subgroup), we measured the protein expression of IL-1β in the blood." (PMID 30504920, 2018). "Unlike what we found in the VAT, we observed higher serum IL-1β levels in obese patients with anxiety or mood disorders than in the non-MD subgroup (0.046 ± 0.080 and 0.132 ± 0.055 pg/mL, respectively) after controlling for BMI." (PMID 30504920, 2018). "Indeed, IL1-β has been previously demonstrated to control the sensitivity of CB1R on GABAergic transmission and to induce anxiety-like behavior in naïve mice." (PMID 27589957, 2016). "ZSSF treatment dramatically reduced anxiety-like behaviors, exerted sedative–hypnotic effects, increased hippocampal 5-HT and 5-HTP, and enhanced intestinal barrier function through inhibiting colon ZO-1, Claudin-1, and Occludin expression and reducing TNF-α, IL-6, and IL-1β levels." (PMID 40077533, 2025). "Furthermore, peripheral administration of IL‐1β did not affect general motor activity or anxiety‐like behavior in young adult C57BL/6J mice (3–4 months old)." (PMID 39996443, 2025). "Our results indicated that a single administration of IL‐1β did not affect the animals' overall exploration behavior or anxiety levels in the open field test (OFT), as evidenced by similar total distances traveled and time spent in the center zone between the vehicle and IL‐1β‐treated groups." (PMID 39996443, 2025). "Anxiety-like behaviors could not be observed in cKO mice after CFA injection with IL-1β and TNF-α levels not remarkedly increasing." (PMID 39337650, 2024). "Indeed, IL-1β expression in SRF was positively correlated with social withdrawal and anxiety-like behavior, supporting the notion that SRF may be part of a common network regulating both behaviors." (PMID 37284463, 2023). "Nevertheless, anxiety was not correlated to IL-1β at any time point (all P>0.05)." (PMID 37878890, 2023). "In our model, even in the absence of direct penetration of PA into the brain, infected mice developed anxiety-like behaviors, which might result from cerebral microvascular dysfunction, BBB leakage, and systemic/local production of cytotoxic cytokines like IL-1β and TNF-α as previously documented." (PMID 37245027, 2023).
Anxiety (continued). "While combined TNF-α and IL-1β administration failed to significantly modulate sickness- and anxiety-like behaviors in the EPM and LDB tests, although there was a trend for less distance travelled by cytokines that was absent in mice pre-treated with the GPR120 agonist." (PMID 38111048, 2023). "Furthermore, high TNF-α (P<0.001, adjusted P <0.001) and increased IL-17 (P=0.014, adjusted P=0.056), but not IL-1β (P=0.648, adjusted P=1.000) or IL-6 (P=0.131, adjusted P=0.524), were correlated with increased anxiety severity grade." (PMID 35239774, 2022). "In conclusion, despite the limitations related to the lack of IL-1β blood level measurement in this clinical study, our results suggest that the consumption of probiotics mitigates anxiety symptoms, especially in healthy adults with the minor A allele of rs16944 as a risk factor." (PMID 32377159, 2020). "Although our results showed a reduction in IL-1β expression in the hippocampus 4 h after LPS administration in α2+/G301R animals, we observed that that α2 haploinsufficiency does not affect the LPS-induced effect on memory impairment and anxiety." (PMID 32843655, 2020). "Post hoc comparisons revealed that non-obese patients diagnosed with anxiety or mood disorders (A/MD subgroup) had significantly higher mRNA levels of IL-1β (P < 0.01), IL-6 (P < 0.01) and PLAUR (P < 0.001 and P < 0.05, respectively) than non-obese patients without mental disorders (non-MD)." (PMID 30504920, 2018). "Since the IL-1β model of inflammation we used in our study shows behavioral modifications such as anxiety-like behaviors and social interaction deficits without motor disabilities, similar to what is observed in ASD, our findings may in part explain these features seen in ASD." (PMID 40909354, 2025). "Also, in order to associate impaired synaptic plasticity across the SDMN with the comorbidity of social impairment and increased anxiety levels, we analyzed the expression of IL-1β in different nodes within the SDMN to link altered cytokine profile with excitatory/inhibitory ratio." (PMID 37284463, 2023). "Moreover, the presence of excessive IL-1β expression in neurons and astroglia, within key nodes of the SDMN, as well as the colocalization with β2-ARs, is suggested to serve as an additional pathophysiological mechanism contributing to social withdrawal and anxiety-like behavior." (PMID 37284463, 2023). "In addition, the anxiety phenotype was not rescued by Il1b KO mice." (PMID 34258564, 2021). "Anxiety was exacerbated in EAE mice lacking CB1Rs, and both the anxiety-like phenotype and striatal CB1R sensitivity were rescued in EAE mice by central inhibition of IL-1β signaling with IL-1ra." (PMID 27589957, 2016).